APOE (apolipoprotein E)
Diseases named in the same sentence as APOE in open-access papers (continued):
Sharing a sentence is not in itself a finding about the gene and the disease.
dementia (continued). "However, the proportions of APOE ε4 carriers, and of incident dementia and MCI in the two early decline groups (classes 3 and 4) were greater over the entire follow up period compared to the later decline groups." (PMID 40636900, 2025). "Given these previous studies, we sought to understand how genetic associations in ADRD could change depending on the definition of dementia, using APOE as an example for an effect likely present in many genes." (PMID 40568661, 2025). "Taken together, these findings suggest that while APOE shapes AD pathology through shared biological mechanisms, racial disparities in dementia expression may depend more on environmental and social modifiers than on differences in molecular biology." (PMID 41268805, 2025). "Earlier studies on this cohort showed that the APOE ε4 allele was associated with accelerated cognitive decline and earlier onset of dementia compared to non-carriers." (PMID 40275327, 2025). "APOE ɛ4 allele carriers had significantly higher rate of all-cause (excluding vascular) dementia diagnosis compared to non-carriers (HR 1.9, 95% CI 1.2, 3.0, P = 0.009)." (PMID 40677699, 2025). "The Authors in their study investigated the link between OSA and dementia risk and identified that only individuals without the apoE ε4 allele and presenting OSA were at risk for cognitive decline." (PMID 40782185, 2025). "However, the earlier, faster decline group (class 2) had a higher proportion of APOE ε4 carriers and greater proportion of incidence of dementia and MCI during follow-up." (PMID 40636900, 2025). "Nevertheless, our study replicated APOE’s role in dementia risk, an effect not observed for the death outcome." (PMID 41206104, 2025). "In addition to varying by sex, the association of BPV with dementia and CIND differed by ApoE ɛ4 carrier status." (PMID 41109864, 2025). "We performed plasma proteomic profiling using SOMAscan to measure 1305 proteins in 53 elderly subjects without dementia homozygous for APOE3 or APOE4, which facilitated identification of APOE‐associated or amyloid‐associated plasma proteins." (PMID 39689057, 2025). "Long-term exposure to PM2.5 was also linked to an increased risk of dementia, regardless of APOE genotype." (PMID 40904564, 2025). "Given APOE’s role in AD risk, a better understanding of its relationships with T2DM and CVD may clarify the contribution of cardiometabolic health to dementia risk and provide insights into prevention and treatment approaches." (PMID 39364911, 2025). "Previous study has also indicated that healthy dietary pattern plays different roles in reducing risk of dementia between APOE ε4 carriers and non-carriers." (PMID 39890535, 2025). "Consistent with previous studies, we found that tea consumption was consistently associated with dementia regardless of genetic predisposition of APOE ε4 carrier status or non-APOE polygenic risk." (PMID 41306653, 2025). "MIND showed modest but consistent advantages (higher model fit, unique separation of MCI progressive versus controls, and more robust sex‐specific APOE effects), but CT and GM provided strong discrimination for AD and were valuable for characterizing dementia‐related changes." (PMID 41451870, 2025). "There was no statistical evidence of an interaction between eBMD and APOE genetic risk (P =.14), indicating that the association between eBMD and incident dementia did not vary on the basis of genetic risk." (PMID 40668308, 2025). "Role of serial inflammatory markers, apolipoprotein E4 (APOE-ε4) status, and dementia subtypes." (PMID 40842786, 2025). "Follow‐up analyses indicated that this association was specific to APOE ε4 carriers, consistent with evidence linking APOE ε4 to late‐life depression (independent of dementia)." (PMID 40476544, 2025). "Cerebral blood flow (CBF) deficits, cognitive decline, and brain structural changes have been reported in older adults with and without apolipoprotein E-e4 (APOE4)-related risk for dementia." (PMID 40220152, 2025).
dementia (continued). "Consistent with the prior study, we found reduced plasma APOE levels were associated with white matter damage, CMBs, and increased risk of all-cause dementia independent of APOE genotypes." (PMID 39818967, 2025). "Four studies found that the association between DSI and dementia was only significant in APOE e4 non-carriers." (PMID 41014505, 2025). "Our results contrast with several studies that have found that PGSs did not improve prediction over and above APOE ε4 status for AD and all-cause dementia (ACD), or for measures of Aβ deposition." (PMID 41282187, 2025). "Regression analyses were conducted with dementia risk factors predicting cognition at 90 + years, adjusting for age, sex, education, follow-up time, and apolipoprotein E genotype (ε4-carrier vs non-carriers)." (PMID 41032471, 2025). "In models adjusting for age and Aβ pathology, APOE ε4 carriership was associated with a higher prevalence of tau positivity in the temporal cortex in all diagnostic groups (β = 0.55 for CU, β = 0.64 for MCI and β = 0.59 for dementia; all P < 0.001)." (PMID 40670684, 2025). "Moreover, a gene dose response was evident across informant‐based cognitive status, with the frequency of neuropathological AD diagnosis in APOE ε4 homozygotes ranging from 38% in cognitively normal individuals to 86% in those with dementia." (PMID 41268805, 2025). "Model 1 (covariates only) indicated that older age, female sex, APOE ε4 carrier status, parental history of dementia, lower GDS score, lower MMSE score, and higher CFI score (i.e., more cognitive complaints) were all significantly associated with elevated amyloid burden." (PMID 40476544, 2025). "APOE ε4 is well-known to increase risk of dementia, and it has been shown to attenuate the protective association of fish oil supplements (FOS) and the incidence of dementia." (PMID 40949174, 2025). "The cohort was balanced with respect to sex and education (both p > 0.05) with expected differences in APOE ε4 dosage, Clinical Dementia Rating Scale Sum of Boxes (CDR-SB), Mini Mental State Exam (MMSE), and Montreal Cognitive Assessment (MoCA) scores (all p < 0.001)." (PMID 40443531, 2025). "Since the APOE SNP associations largely replicated in BioVU, we conducted mediation analyses to examine whether these associations are mediated by MCI/dementia." (PMID 39974048, 2025). "Another study examined the individual and joint influence of diabetes status, apolipoprotein E (APOE) ε4, and PA on the risk of dementia and cognitive impairment without dementia (CIND) in cognitively normal older adults." (PMID 40274715, 2025). "Future research is needed to illuminate the specific mechanisms by which APOE relates to T2DM and CVD risks, and also how APOE-related susceptibility to these cardiometabolic conditions might contribute to subsequent dementia risk." (PMID 39364911, 2025). "Nevertheless, these studies used convenience samples, enriched for White participants and dementia diagnoses, and therefore may overestimate the penetrance of APOE ε4." (PMID 41268805, 2025). "First, higher mtDNAcn is associated with a reduced risk of dementia, especially non-AD dementia, independent of demographics and APOE ε4 carrier status." (PMID 39313624, 2025). "Additionally, a similar effect of lower eBMD on incident dementia was observed across all stratified categories by sex and APOE status, suggesting that the main effects of eBMD better explain the impact on dementia risk." (PMID 40668308, 2025). "In AD, for example, the addition of GFAP and ApoE genotype to plasma p-tau217 significantly improved the prediction of amyloid positivity, while cognitive metrics further enhanced the prediction of progression to dementia." (PMID 40640892, 2025).
dementia (continued). "This study found that in cognitively unimpaired older adults, higher levels of concern about developing AD were associated with higher amyloid burden after adjusting for demographics, depression, cognitive performance, parental history of dementia, and APOE ε4 status." (PMID 40476544, 2025). "The relevance of APOE ε4 is emphasized by its links to dementia." (PMID 41180817, 2025). "However, it is much less clear how APOE genotype contributes to the decrease in cerebral blood flow that is observed before the onset of dementia." (PMID 39880935, 2025). "Regarding racial differences (Black and White individuals), the same effect was observed: people at high social disadvantage presented the greatest risk of dementia, regardless of APOE allele." (PMID 41264567, 2025). "Demographics, neuropathological features, APOE, and dementia status of participants." (PMID 40843926, 2025). "Relationships between APOE and incidence of T2DM and CVD are not fully understood but may shed light on the mechanisms underlying dementia pathogenesis." (PMID 39364911, 2025). "It is thus likely that peripheral apoE regulates the systemic environment in an allele‐dependent manner, though characterization of how APOE4 affects the plasma proteome in elderly subjects without dementia is lacking." (PMID 39689057, 2025). "APOE genotype was available for 1939 participants (PREVENT Dementia: 573, ALFA‐MRI: 1366)." (PMID 40356022, 2025). "A 15-year follow-up study from two cohorts in the UK and France reported that carrying the ApoE ε4 allele was associated with an 89% increased risk of dementia compared to non-carriers." (PMID 40717068, 2025). "Regarding individual social determinants, having a lower education level and lower family income presented the strongest interactions and were associated with a greater risk of dementia, regardless of APOE allele group." (PMID 41264567, 2025). "Many studies have supported the notion, including those that revealed significantly lower cognitive domain scores, or higher odds of subsequent dementia and earlier dementia onset among PD APOE ε4 carriers, and longitudinal studies revealing a more rapid decline in PD APOE ε4 carriers." (PMID 41180817, 2025). "This may be due to factors such as large heterogeneity in the Hispanic/Latino population, small sample sizes, other methodological limitations such as reliability of APOE genotyping data in meta‐analyses, or racial biases when assessing dementia." (PMID 40501118, 2025). "Structural inequalities are similar in Brazil and the US, with Black Brazilians experiencing greater socioeconomic disadvantage, which itself may modify the relationship between APOE genotype and dementia." (PMID 41268805, 2025). "By contrast, Apolipoprotein E allele E4 (ApoE4) status makes some subtypes of dementia more likely but provides no information about a patient’s stage." (PMID 41326296, 2025). "The risk of dementia increased significantly if people with SCD were recruited from a memory clinic, and even more so if the person had a low score on the MMSE and the presence of APOE-4." (PMID 41368162, 2025). "Beyond the well-known genetic risk factor for AD, the presence of the Apolipoprotein E (APOE) ε4 allele, several lifestyle and acquired clinical conditions are recognised as modifiable risk factors for dementia, many of which are associated with elevated inflammatory processes." (PMID 39807297, 2025). "However, sizeable minorities of APOE‐ε4 carriers within 5 years of parental dementia onset and beyond parental dementia onset remained amyloid negative." (PMID 40018326, 2025). "It is noteworthy to mention that although processed meat consumption was associated with an increased risk, the APOE ε4 allele increased dementia risk between three and six times without modifying dietary associations significantly." (PMID 39861466, 2025).
dementia (continued). "Specifically, for the cycling and mixed-cycling groups, the risk of all-cause dementia was lower among those without APOE ε4 (HR, 0.74 [95% CI, 0.63-0.87]) compared with those with APOE ε4 (HR, 0.88 [95% CI, 0.76-1.02])." (PMID 40489111, 2025). "In stratified analyses, the greater risk of dementia for non-recallers was maintained in APOE e4 carriers but not in non-carriers." (PMID 41001478, 2025). "This may be because APOE ε4 is a strong determinant of earlier symptom onset, meaning dementia cases in the younger cohort had a stronger genetic component, potentially masking the additional contribution of neuroticism." (PMID 41275373, 2025). "Thus, we were unable to directly assess the temporal sequence linking APOE genotype, pathology accumulation, and conversion to clinical dementia." (PMID 41268805, 2025). "Although the role of APOE ε4 role in moderating the effect of clusters of multimorbidity on dementia remains inconsistent, research suggests that preventing multimorbidity could help reduce dementia risk, particularly in non‐carriers." (PMID 40990184, 2025). "In this study, higher midlife physical activity was only associated with lower dementia risk among APOE ε4 allele noncarriers, whereas late-life physical activity was associated with dementia risk among both ε4 carriers and noncarriers." (PMID 41259024, 2025). "The association between high BPV and risk of dementia or CIND in males was attenuated in those carrying the APOE ɛ4 allele; however, males lacking the ɛ4 allele remained at increased risk of CIND." (PMID 41109864, 2025). "Furthermore, these data highlight the importanceof blood pressure management, particularly in females and APOE-ε4carriers, as a potentially high impact, scalable strategy for dementia prevention." (PMID 40196000, 2025). "In the PREVENT Dementia cohort, we have previously shown that APOE ε4 carriers have increased cerebral perfusion, a smaller molecular layer of the hippocampus, increased cerebral microbleeds, and that a larger posterior thalamus is associated with worse immediate recall." (PMID 40356022, 2025). "The risk of dementia among participants with hearing loss was much greater in APOE ε4 allele carriers than in those without an APOE ε4 allele, an interesting gene-environment interaction." (PMID 41191359, 2025). "Women with moderate-to-high AAC have double the risk of dementia in later life, and this risk is not related to cardiovascular risk factors and apolipoprotein E (APOE) genotype." (PMID 40153574, 2025). "The results indicate a risk reducing effect of adhering to the EAT-Lancet diet among APOE ε4 non-carriers, and no negative effects on dementia risk were detected." (PMID 40222839, 2025). "Thus, the form of TMCC2 present in the human brain was found to differ according to brain region as well as according to APOE and/or dementia status." (PMID 39084860, 2025). "Some studies have found that the increased risk of dementia associated with AF is more pronounced in non-carriers of the APOE e4 allele, with no such association observed in individuals with at least one APOE e4 allele." (PMID 39981345, 2025). "Higher social adversity will be associated with elevated dementia risk, regardless of APOE genotype." (PMID 41264567, 2025). "Consistent with the lack of association of Aβ pathology with GBA-PD, APOE E4 status does not predict dementia in this group, in contrast to iPD." (PMID 40722695, 2025). "All 4 neuroimaging markers combined mediated only 6% of the effect of APOE ε4 on dementia, suggesting either that cognition as an outcome better captures the mediated variation than dementia or that cognition is more profoundly affected by the studied mediators." (PMID 40344552, 2025). "The need for more research was the conclusion of a review that assembled results from 65 cross-sectional and 46 longitudinal studies of the association between APOE variants and cognitive test scores in people without cognitive impairment or dementia." (PMID 40386430, 2025).
dementia (continued). "Potentially, APOE ε4 carriership may intervene on pathways linking diet with dementia (e.g., cholesterol metabolism), attenuating the protective effects of a healthy diet." (PMID 40222839, 2025). "APOE was the locus shared among these three dementia outcomes." (PMID 40949174, 2025). "At the protein level, western blots of human brain extracts revealed that human brain‐derived TMCC2 exists as at least three isoforms, the relative abundance of which varied between the temporal gyrus and cerebellum and was influenced by APOE and/or dementia status." (PMID 39084860, 2025). "The moderation analysis indicated that the association between marital status and incident dementia did not vary across race, education, depression, the presence of the APOE ε4 allele, and the primary reason for visiting the ADRCs." (PMID 40110684, 2025). "The proportion of APOE‐ε4+/APOE‐ε2‐ subjects who were amyloid‐positive additionally meeting criteria for p‐tau positivity did not appear to rise substantially on approach of age of parental dementia onset." (PMID 40018326, 2025). "Each additional CMP location was associated with a higher dementia risk in APOE ɛ4 carriers (HR, 1.13, 95% CI: 1.09–1.17) compared to non-carriers (HR, 1.07, 95% CI: 1.03–1.11)." (PMID 40101131, 2025). "A risk-reducing effect was observed among APOE ε4 non-carriers with three of the scores in relation to AD, and with five of the scores in relation to all-cause dementia." (PMID 40222839, 2025). "Another concept posits that vascular pathology compromises BBB integrity, leading to dementia irrespective of Aβ and tau pathology, particularly in carriers of the APOE ε4 allele." (PMID 41008597, 2025). "To analyze which factors might influence plasma p‐tau181 levels, we ran a multiple backward regression analysis, considering diagnosis (SCD, MCI, AD dementia), age at plasma collection, Core1 status, impaired renal function, and APOE genotypes as covariates." (PMID 40928125, 2025). "Although the link between CMP and dementia is well-documented, our study is among the first to investigate whether this relationship is modified by APOE ɛ4 genotype." (PMID 40101131, 2025). "The APOE genotype, a key genetic factor in dementia risk, was coded as APOE ɛ4 non-carriers or APOE ɛ4 carriers." (PMID 40101131, 2025). "The results indicated a reduced risk of AD and all-cause dementia among APOE ε4 non-carriers, but not among APOE ε4 carriers." (PMID 40222839, 2025). "In ApoE-genotyped participants, high BPV was associated with dementia in females and cognitive decline in males when the ɛ4 allele was absent, and cognitive decline in females regardless of ɛ4 carrier status, suggesting a mechanism of risk partially independent to the effects of ApoE ɛ4." (PMID 41109864, 2025). "We secondarily aimed to examine how person-specific dementia risk factors,such as age, sex, and AD risk gene apolipoprotein ε4(APOE-ε4) carrier status (yes/no), influence the relationshipsbetween blood pressure and key biomarkers of brain aging." (PMID 40196000, 2025). "Previous studies have suggested that the potential associations of individual CR proxies with dementia and MCI might vary by demographic features and genetic susceptibility (i.e., apolipoprotein E [APOE] genotypes)." (PMID 38779828, 2024). "First, several major YOD risk factors, such as APOE ε4 alleles; APP, PSEN1, and PSEN2 genes; family history of dementia; history of traumatic brain injury; hearing loss; and education level could not be obtained." (PMID 38926887, 2024). "In the current study, we found that neuroticism was consistently associated with dementia regardless of genetic predisposition to dementia based on either APOE ε4 carrier status or non‐APOE polygenic risk." (PMID 38984680, 2024).